CCT5 (chaperonin containing TCP1 subunit 5)
Description:
Component of the chaperonin-containing T-complex (TRiC), a molecular chaperone complex that assists the folding of actin, tubulin and other proteins upon ATP hydrolysis. The TRiC complex mediates the folding of WRAP53/TCAB1, thereby regulating telomere maintenance. As part of the TRiC complex may play a role in the assembly of BBSome, a complex involved in ciliogenesis regulating transports vesicles to the cilia.
Synonyms: TCP-1-epsilon; CCTE; KIAA0098; CCT-epsilon; HEL-S-69; HSNSP; PNAS-102
Tractability: Small molecule: a structure with a bound ligand is known. PROTAC: UniProt records ubiquitination sites on it; ubiquitination databases record sites on it; its protein half-life has been measured.
Gene: Protein-coding gene on chromosome 5 (10,249,929 to 10,266,389, forward strand). Ensembl gene ENSG00000150753.
Subcellular location: Cytoplasm; Cytoplasm, cytoskeleton, microtubule organizing center, centrosome
Subcellular location (Human Protein Atlas): Mid piece; Annulus; Principal piece
Pathways (Reactome):
Metabolism of proteins: Association of TriC/CCT with target proteins during biosynthesis; Cooperation of PDCL (PhLP1) and TRiC/CCT in G-protein beta folding; Folding of actin by CCT/TriC; Formation of tubulin folding intermediates by CCT/TriC; Prefoldin mediated transfer of substrate to CCT/TriC
Organelle biogenesis and maintenance: BBSome-mediated cargo-targeting to cilium
Gene Ontology:
Molecular function: ATP hydrolysis activity; beta-tubulin binding; G-protein beta-subunit binding; mRNA 3'-UTR binding; mRNA 5'-UTR binding; protein binding; protein folding chaperone; ATP binding; ATP-dependent protein folding chaperone
Biological process: positive regulation of protein localization to Cajal body; positive regulation of telomerase RNA localization to Cajal body; positive regulation of telomere maintenance via telomerase; protein folding; protein stabilization; response to virus
Cellular component: centrosome; chaperonin-containing T-complex; cytoplasm; extracellular exosome; microtubule; cytosol; cell body
Genetic constraint (gnomAD): Loss-of-function variants: 6 observed, 50.34 expected, observed/expected ratio (o/e) 0.12, 90% interval 0.064 to 0.23. The upper end of that interval is the gene's LOEUF score, 0.23, which puts it in group 1 of 6, group 1 being the genes least tolerant of losing a copy. Missense variants: 514 observed, 682.04 expected, observed/expected ratio (o/e) 0.75, 90% interval 0.7 to 0.81. Synonymous variants: 226 observed, 242.27 expected, observed/expected ratio (o/e) 0.93, 90% interval 0.84 to 1.04.
Homologues: Orthologues: chimpanzee CCT5 (100% identical), macaque CCT5 (100% identical), rabbit CCT5 (99% identical), dog CCT5 (98% identical), pig CCT5 (98% identical), guinea pig CCT5 (97% identical), mouse Cct5 (96% identical), rat Cct5 (92% identical), zebrafish cct5 (87% identical), tropical clawed frog cct5 (84% identical), Drosophila melanogaster CCT5 (70% identical), Caenorhabditis elegans cct-5 (68% identical). Paralogues in human: CCT4 (37% identical), TCP1 (34% identical), CCT2 (32% identical), CCT3 (30% identical), CCT6B (29% identical), CCT6A (29% identical), CCT8 (29% identical), CCT7 (28% identical), PIKFYVE (24% identical), CCT8L2 (22% identical), HSPD1 (18% identical), BBS12 (16% identical), and 1 more.
Diseases named in the same sentence as CCT5 in open-access papers:
CCT5 is named in the same sentence as 59 diseases in open-access papers, as found by Europe PMC text mining. Sharing a sentence is not in itself a finding about the gene and the disease. The quoted sentences say what the papers report.
breast carcinoma (9 papers, 2020 to 2025). "For example, CCT2, CCT3, CCT4, and CCT5 were increased in breast cancer cells and positively correlated with tumor progression." (PMID 40374617, 2025). "In breast cancer, the knockdown of CCT5 leads to increased apoptosis after docetaxel treatment." (PMID 37953237, 2023). "Similarly, CCT5 siRNA knockdown increased docetaxel-induced apoptosis of MCF-7 breast cancer cells, suggesting that this knockdown strategy may potentiate the efficacy of anticancer drugs." (PMID 34676169, 2021).
gastric cancer (8 papers, 2021 to 2024). A primary or metastatic malignant neoplasm involving the stomach. "In a recent study performed by Li and colleagues, chaperon-containing TCP1 subunit 5 (CCT5) was shown to bind E-cadherin cytoplasmic domain overriding its interaction with β-catenin in gastric cancer cells." (PMID 38372877, 2024). "CCT5 markedly promotes gastric cancer cell proliferation, anoikis, invasion, and lymphatic tube formation." (PMID 37114037, 2023). "CCT5 markedly promotes gastric cancer anti-anoikis to promote gastric cancer lymph node metastasis formation." (PMID 37114037, 2023). "Recently, a study reported that CCT5 induced epithelial-mesenchymal transition (EMT) to promote gastric cancer lymph node metastasis, and another study reported it promoted lung adenocarcinoma cell migration and invasion." (PMID 36589233, 2022). "CCT5 promotes tumour progression in gastric cancer by inducing EMT and activating the Wnt pathway." (PMID 37859585, 2023). "Upregulated CCT5 could induce epithelial-mesenchymal transition to promote gastric cancer lymph node metastasis by activating the Wnt/β-catenin signaling pathway." (PMID 37006287, 2023). "CCT5 expression was elevated in multidrug-resistant gastric carcinoma cells." (PMID 37953237, 2023). "In addition, CCT5 was also overexpressed in sinonasal adenocarcinoma 67, esophageal squamous cell carcinoma 68 and multidrug-resistant gastric carcinoma cells." (PMID 34522182, 2021). "Therefore, CCT5 promotes gastric cancer proliferation and metastasis." (PMID 38372877, 2024). "Chaperonin-containing T-complex protein 1ε subunit (CCT5) binds to E-cadherin and abrogates the interaction between E-cadherin and β-catenin, releasing β-catenin into the nucleus, leading to the EMT in gastric cancer cells and facilitating gastric cancer progression and lymphatic metastasis." (PMID 38952556, 2024).
Sensory neuropathy (6 papers, 2016 to 2023). Peripheral neuropathy affecting the sensory nerves. "A mutation in cct2 has been found in a family with Leber congenital ameurosis retinal phenotype and mutations in cct4 and cct5 have been related to sensory neuropathy." (PMID 30777146, 2019). "Mutated CCT4/5 subunits cause sensory neuropathy and CCT5 expression is decreased in Alzheimer's disease." (PMID 27929117, 2016). "In addition, the CCT5 subunit is of special interest because the mutation of histidine-147 to arginine (H147R) in the human CCT5 gene is associated with autosomal recessive mutilating sensory neuropathy with a spastic paraplegia disease." (PMID 28623285, 2017).
hepatocellular carcinoma (5 papers, 2021 to 2026). A malignant tumor that arises from hepatocytes. "For example, there is a significant difference in the expression of TCP1/CCT2/CCT3/CCT4/CCT5/CCT6A/CCT7/CCT8 in hepatocellular carcinoma." (PMID 37058032, 2023). "In hepatocellular carcinoma, miR-139-5p can regulate the proliferation, migration and invasion of hepatocellular carcinoma cells by targeting different targets such as SLITRK4, CCT5 and ARF6." (PMID 35386287, 2022). "Five genes (PSRC1, SOCS2, TMEM45A, CCT5, and STC2) were selected from the TCGA training dataset to construct the prognostic CSGscore signature, which could precisely predict the prognosis of hepatocellular carcinoma patients both in the training and validation datasets." (PMID 36589233, 2022).
hereditary sensory neuropathies (4 papers, 2013 to 2023). "Of particular health-related interest is the mutation Histidine 147 to Arginine (H147R) in human TRiC subunit 5 (CCT5), which has been associated with hereditary sensory neuropathy." (PMID 28623285, 2017). "Interestingly, mutations in the TRiC subunits CCT4 and CCT5 are associated with hereditary sensory neuropathies implicating that dysfunction of TRiC in axons from lyso-Gb3 exposure could be a contributor to the peripheral neuropathy observed in FD." (PMID 37145097, 2023).
lung carcinoma (4 papers, 2012 to 2024). "For instance, based on the soft clustering method and nested comparisons, we found that MUC5B and SELL have potential diagnostic values for lung cancer cases of BM, and the best accuracy was achieved when separating cases of BM and LA from LM using the combination of APOH, CD81, and CCT5." (PMID 37770976, 2023). "Apart from that, CCT5 was identified to be closely related to lung cancer." (PMID 33869000, 2021). "Numerous studies have examined the role of CCTs, such as CCT3, CCT5, and CCT6A, in lung cancer, particularly NSCLC." (PMID 39259093, 2024).
non-small cell lung carcinoma (4 papers, 2017 to 2021). A group of at least three distinct histological types of lung cancer, including non-small cell squamous cell carcinoma, adenocarcinoma, and large cell carcinoma. "CCT5 was a tumor associated antigen of non-small cell lung cancer (NSCLC)." (PMID 33815471, 2021).
ovarian carcinoma (4 papers, 2020 to 2025). A malignant neoplasm originating from the surface ovarian epithelium. "The expression of CCT5 in ovarian cancer, colon cancer, clear cell RCC, clear cell RCC (extended), UCEC, lung adenocarcinoma, lung squamous cell carcinoma, and head and neck squamous carcinoma was significantly higher than in normal samples." (PMID 40274875, 2025). "Through further analysis of these key genes and cancer stem cell subpopulation, more critical genes can be obtained as LCP2, FCGR3A, COL1A1, COL1A2, MT-CYB, CCT5, and PAPPA, are closely associated with ovarian cancer." (PMID 35360863, 2022). "CCT5 can be used as a prognostic marker of ovarian cancer and can improve the prognosis of ovarian cancer." (PMID 35360863, 2022). "The prognostic potential of the CCC-related biomarkers was validated in an external gene expression dataset (KM plotter) for OS of ovarian cancer patients (n = 655 for CCT5, KCTD10, and SETD3; n = 1,656 for the remaining CCC-related biomarkers)." (PMID 32133296, 2020). "Furthermore, analysis of data from the Kaplan–Meier plot showed a correlation between higher expression of TCP1, RPL5, HSPA4, and CCT5 and poor prognosis in ovarian cancer." (PMID 39309198, 2024). "Through the analysis of stemness-related key genes and tumor stem cell subpopulations, LCP2, FCGR3A, COL1A1, COL1A2, MT-CYB, CCT5, and PAPPA are closely related to ovarian cancer." (PMID 35360863, 2022). "In our new analytical process, the key genes related to ovarian cancer are identified as LCP2, FCGR3A, COL1A1, COL1A2, MT-CYB, CCT5, and PAPPA, which may have important significance in ovarian cancaer and drug therapy." (PMID 35360863, 2022). "Therefore, COL1A1, COL1A2, MT-CYB, CCT5, and PAPPA may be potential genetic biomarkers for the treatment of ovarian cancer." (PMID 35360863, 2022).
lung adenocarcinoma (3 papers, 2017 to 2025). A carcinoma that arises from the lung and is characterized by the presence of malignant glandular epithelial cells. "The expression pattern of CCT5 in lung adenocarcinoma was the same as that in squamous cell lung carcinoma." (PMID 28969060, 2017). "In this study, we found that mutations in CCT5 are most common in LUSC (> 10%), followed by Esophageal Adenocarcinoma (EAC), Bladder Urothelial Carcinoma (BLCA), and Lung Adenocarcinoma (LUAD), which cumulatively indicates that CCT5 mutations influence cancer progression in different tissues." (PMID 40274875, 2025). "The expression of CCT5 in tumor tissues from 20 patients with squamous cell lung carcinoma and 20 patients with lung adenocarcinoma and their adjacent non-tumor tissues were assessed immunohistochemically and by western blot using goat anti-mouse monoclonal antibody." (PMID 28969060, 2017).
neuropathy (3 papers, 2012 to 2025). A disorder affecting the nervous system that manifests with pain, tingling, numbness, and/or muscle weakness. "Here, we are elucidating the mechanism of a heritable CCT5 subunit mutation that causes profound neuropathy in humans." (PMID 29552646, 2017). "The CCT5 gene variations were reported to be associated with neuropathy." (PMID 40572705, 2025).
breast tumors (2 papers, 2018 to 2020). "While CNA events in deep or shallow depletion rarely or less occurred, EGFR, MYC, IRF2BP2, ASAP1, and CCT5 (except for DRD1) often underwent copy gain and amplification, acquiring CNA-driven expression in the breast tumors." (PMID 32235890, 2020). "We next sought to address the correlation between CNA frequencies and expression levels of MYC, EGFR, ASAP1, IRF2BP2, CCT5, and DRD1 in broad BC cell lines and breast tumors and the clinical relevance of the genes to patients with BC." (PMID 32235890, 2020).
COVID-19 (2 papers, 2022 to 2025). A disease caused by infection with severe acute respiratory syndrome coronavirus 2. "Remarkably, telomere maintenance processes were observed to be one of the top biological processes activated in patients with mild COVID-19 via activation of genes such as CCT2, CCT3, CCT4, CCT5 and CCT6A." (PMID 41141600, 2025).
distal motor neuropathy (2 papers, 2022 to 2023). "Here, we present a succinct review of the most salient abnormalities of skeletal muscle, based on our earlier report of a patient who carried a mutation in the chaperonin CCT5 subunit and suffered from a distal motor neuropathy of early onset." (PMID 37237456, 2023). "For instance, the His147Arg CCT5 mutation is associated with a mutilating sensory distal neuropathy, whereas the Leu224Val mutation is associated with an early onset distal motor neuropathy." (PMID 37237456, 2023). "Here, we review recent findings in muscle tissue of a CCT5 chaperonopathy characterized by the Leu224Val mutation accompanied by distal motor neuropathy of early onset." (PMID 37237456, 2023). "More recently, we reported a different genetic variant of CCT5 that was associated with a severe distal motor neuropathy, which is the object of this article." (PMID 35720129, 2022). "Here, histological features of skeletal muscle from a patient with a severe, early onset, distal motor neuropathy, carrying a mutation on the CCT5 subunit (MUT) were examined in comparison with normal muscle (CTR)." (PMID 35720129, 2022). "In this report, we deal with a disease that according to clinical signs and symptoms is a genetic, early onset, distal motor neuropathy, associated to a mutation in a chaperone gene, the subunit CCT5 of the chaperone complex CCT." (PMID 35720129, 2022).
glioblastoma (2 papers, 2019 to 2024). The most malignant astrocytic tumor (WHO grade IV). "AP1B1, adaptor related protein complex 1 beta 1 subunit; CAPZA2, F-actin-capping protein subunit alpha-2; CCT5, chaperonin containing TCP1 subunit 5; GBAS, glioblastoma amplified sequence; RPS21, 40 S ribosomal protein S21." (PMID 30931934, 2019). "Identified were five fasting-responsive proteins that overlapped between the lines, including adaptor related protein complex 1 beta 1 subunit (AP1B1), CAPZA2, chaperonin containing TCP1 subunit 5 (CCT5), glioblastoma amplified sequence (GBAS), and 40 S ribosomal protein S21 (RPS21)." (PMID 30931934, 2019).
intellectual disabilities (2 papers, 2022 to 2025). "However, CCT5 is implicated in the cellular pathways related to trafficking to the periciliary membrane and cell cycle and has also been linked to intellectual disabilities and early onset motor neuropathies." (PMID 36232428, 2022). "Recent reports provide evidence for presence of variants in several TRiC/CCT members including CCT1, CCT3, CCT5, CCT6A, CCT7 and CCT8, in brain malformations, seizures, and intellectual disability." (PMID 40779003, 2025).
lung squamous cell carcinoma (2 papers, 2017 to 2025). "The rates of positive expression of CCT5 in lung squamous cell carcinoma and adenocarcinoma were 60%(12/20) and 65%(13/20), respectively." (PMID 28969060, 2017). "In squamous cell lung carcinoma, higher expression of CCT5 tended to be localized only in the cytoplasm, and the adjacent non-tumor tissues showed lower or non-expression." (PMID 28969060, 2017).
small cell lung carcinoma (2 papers, 2021 to 2024). Small cell lung cancer (SCLC) is a highly aggressive malignant neoplasm, accounting for 10-15% of lung cancer cases, characterized byrapid growth, and early metastasis. "Knockdown of CCT5, PIP4K2A, EXO1, CMBL, OPN3, and KMO, genes within 200 kb up/downstream of the three SNPs that were corresponded with small cell lung cancer (SCLC) overall survival." (PMID 33869000, 2021).
virus infection (2 papers, 2020 to 2025). "More importantly, both co-IP and immunofluorescence data indicated that avian CCT5 had a favorable association with influenza NP protein under overexpression or viral infection." (PMID 33178142, 2020). "Further investigation showed that viral infection profoundly elevated the expression level of cellular CCT5, whose expression, in turn, promoted the nuclear export of NP, as well as viral polymerase activity, thereby facilitating the replication of IAV." (PMID 33178142, 2020). "Furthermore, we demonstrated that CCT5 expression is largely elevated by H5N6 viral infection, which reversely benefits its proliferation." (PMID 33178142, 2020). "Importantly, mechanical studies revealed that CCT5 promoted the nuclear export of NP and increased the viral polymerase activity during virus infection." (PMID 33178142, 2020).
acute myelogenous leukemia (1 paper, 2022). "Instead, NPM1, which is involved in non-Hodgkin lymphoma and acute myelogenous leukemia, and CCTs (CCT4, CCT5, and CCT7) were up-regulated." (PMID 35464471, 2022).
Ataxia (1 paper, 2022). Ataxia refers to impaired coordination of voluntary muscle movement. "Among the top 10 DMR genes, WDR19 was associated with ataxia, SYCP1 regulated the meiosis progress, FAM173B and CCT5 involved chronic pain." (PMID 36344488, 2022).
Atrophy (1 paper, 2019). Any weakening or degeneration, especially through lack of use. "Individuals with spastic paraplegiamay present with atrophy of the spinal cord and defects in the upper limbs.These results indicate that SLC6A3, CCT5 and TPPP showimportant connection." (PMID 30985858, 2019).
co-infection (1 paper, 2025). "Protein-protein interaction network analysis further delineated pathogen-specific hubs: inflammatory mediators (CXCL8, CCL20, IL6) in the E group, molecular chaperones (CCT5, RUVBL1/2) in the S group, and a distinctive IL6-FBL-centered network in co-infection." (PMID 40771952, 2025).
demyelinating peripheral neuropathy (1 paper, 2023). "Patients carrying the His147Arg mutation in the CCT5 subunit had a demyelinating peripheral neuropathy." (PMID 37237456, 2023).